EPO (erythropoietin)
Diseases named in the same sentence as EPO in open-access papers (continued):
Sharing a sentence is not in itself a finding about the gene and the disease.
tumor (continued). "Although a role for EPO in tumor angiogenesis has been suggested, its potential as a target and direct modulator of pathologic tumor neovascularization is not established." (PMID 17579721, 2007). "Stable expression in tumor cells of a secreted EPO antagonist protein (R103A-EPO) exerts a remarkable anti-angiogenic effect and impairs primary tumor growth both in window chambers and in the mammary fat pad." (PMID 17579721, 2007). "Recent data suggest that recombinant human erythropoietin (rhEPO) modulates tumour growth and therapy response." (PMID 17299396, 2007). "On the other hand, EPO has been shown to exert direct effects on angiogenesis and tumour growth mediated by presence of the EPO receptor on endothelial cells and a number of malignant cell types." (PMID 17299396, 2007). "The present studies show that erythropoietin is an important angiogenic factor that regulates the induction of tumor neovascularization." (PMID 17579721, 2007). "We investigated the role of the hematopoietic cytokine erythropoietin as an angiogenic factor that modulates tumor progression." (PMID 17579721, 2007). "It is possible that the pro-angiogenic properties and modest growth-promoting effects of EPO require sustained and high local concentrations in the tumor microenvironment that cannot be achieved by systemic, intermittent rEPO administration." (PMID 17579721, 2007). "The magnitude of the anti-angiogenic and anti-tumor effects of erythropoietin blockade using R103A-EPO expression is comparable to that achieved by targeting VEGF in window chambers in our previous experiments." (PMID 17579721, 2007). "Our findings suggest that further investigation is warranted to employ erythropoietin blockade for the therapeutic modulation of tumor angiogenesis." (PMID 17579721, 2007). "The contribution of erythropoietin to erythrocytosis in this particular case is unclear, however, the fact that the erythrocytosis was corrected after tumor resection strongly suggests that this was a tumor-related occurence." (PMID 16995951, 2006). "As measured by Ki-67 immunohistochemical staining, there was no statistical difference between the mean proliferation indices between the EPO-treated and control groups in any of the tumour cell lines." (PMID 16288305, 2005). "Tumour volumes were similar between the EPO-treated and control groups in each of the four tumour cell lines throughout the length of the study." (PMID 16288305, 2005). "On the other hand, secondary indirect effects of EPO on the tumour microenvironment (e.g. by increasing the haemoglobin level of the blood and by this improving the oxygen transport capacity) cannot be ruled out in the present study." (PMID 15305198, 2004). "Recent studies have revealed that EPO may contribute to immunosuppressive mechanisms within the tumor microenvironment, thereby reshaping our understanding of its risk/benefit profile in oncology." (PMID 41375075, 2025). "Furthermore, the involvement of hypoxia in radioresistance has also been indirectly demonstrated by the modulation of HIF-dependent gene expression such as EPO (erythropoietin), which is also involved in tumor progression." (PMID 40361506, 2025). "A recent review evaluating evidence supporting the EPO–EPOR tumor-stimulation hypothesis highlighted critical limitations in much of the existing research." (PMID 41268443, 2025). "Notably, HIF-1α primarily regulates genes involved in anaerobic glycolysis and cell death, while HIF-2α controls genes related to erythropoietin (EPO) synthesis and tumor stemness or pluripotency." (PMID 40813760, 2025). "While increased EPO levels may initially enhance oxygen delivery via increased red blood cells, tumor cells can develop functional EPOR." (PMID 38542288, 2024).
tumor (continued). "Finally, to illustrate how the range of tumor genotypes can be readily expanded, we generated EPO-GEMMs by knocking out the Pten tumor-suppressor gene, in accordance with the documented role of PI3K activating mutations in human gastric cancer." (PMID 38177458, 2024). "However, regarding the well-described role of the digestive microbiota on anti-tumor immunity, an indirect effect of EPO on tumor progression through perturbation of the intestinal ecosystem should also be considered." (PMID 39916952, 2024). "Although an exact cause could not be established, the reasons may be changes in iron metabolism, suppression of erythroid progenitor cells by releasing tumor cytokines, impaired erythropoietin response on erythroid progenitor cells, and hemorrhage." (PMID 38929488, 2024). "Interestingly, suppressing EPO signaling in the tumor xenografts of both uterine and breast cancers leads to tumor and endothelial cell death, resulting in tumor size reduction and apoptosis." (PMID 38542288, 2024). "Using both MYC-sgp53 and MYC-sgApc genotypes resulted in tumor formation with similar histological features to those of our non-Cre-restricted tumors, consistent with an epithelial and potentially parietal cell of origin in the EPO-GEMMs." (PMID 38177458, 2024). "Finally, EPO-GEMMs offer the unique capability to readily change the host, which provides a flexible and robust platform to study tumor–host interactions." (PMID 38177458, 2024). "Therefore, the use of anti-CD71 antibody to deplete EPCs resulted in a reduction in tumor-induced erythropoietin production and tumor growth." (PMID 39766202, 2024). "On the other hand, tumor-related inflammation may lead to the release of various inflammatory factors, which may interfere with erythropoietin synthesis and lead to a decrease in HGB." (PMID 37596548, 2023). "Therefore, an increase in hemoglobin and hematocrit values in our patients with early EC can be explained by tumor-induced secretion of erythropoietin, similar to thrombopoietin." (PMID 36626395, 2023). "In addition, EPO-independent cells formed in situ tumours within three weeks of their subcutaneous injection into immunodeficient mice demonstrating their ability for autonomous proliferation." (PMID 37573408, 2023). "The protective and anti‐apoptotic roles of EPO on many cells, including neoplastic ones, were discovered recently and may explain the EPO production phenomenon in some tumours." (PMID 36495211, 2023). "Erythropoietin and its receptor are expressed in various tumor tissues and tumor cells." (PMID 37894821, 2023). "Studies showed that functional EPO receptor signaling was critical for the tumor-promoting growth effects of EPO through in vitro and in vivo experiments, indicating that EPOR expression was positively correlated with the expression of the mitochondrial marker VDAC1 in human NSCLC patient biopsies." (PMID 37746281, 2023). "Accordingly, VEGF and EPO are upregulated, resulting in angiogenesis and supporting tumor growth." (PMID 35769460, 2022). "While our findings promise beneficial effects of EPO, fear has also arisen that treatment of exogenous EPO may accelerate tumor growth in cancer patients in clinical studies." (PMID 36016936, 2022). "Thus, tumor-driven overexpression of certain inflammatory cytokines results in an impaired erythropoietin (EPO) production, an inadequate response of the erythroid progenitors to EPO as well as an altered iron metabolism." (PMID 35694408, 2022). "SPP1 and EPO promote tumor progression in a variety of ways." (PMID 35572724, 2022). "Alongside its influence on the tumor microenvironment, EPO might also have a direct effect on cancer stem cells by increasing the proliferation and self-renewal of these cells." (PMID 35694408, 2022). "Increased expression of EPO has effect on delaying tumor growth could reduce tumor hypoxia and ameliorate the deleterious effects of hypoxia on tumor growth, metastasis and treatment resistance." (PMID 36397112, 2022).
tumor (continued). "In contrast, erythropoietin can interact with S100A2 to enhance tumor development." (PMID 35885660, 2022). "Furthermore, mice harboring primary MPB1 tumors showed significantly improved survival following cisplatin therapy, a result that was recapitulated in mice following subcutaneous or intraperitoneal (i.p.)injection of primary EPO-GEMM tumor-derived cell lines." (PMID 35082152, 2022). "Taken together, due to the widespread use of nonspecific anti-EPOR antibodies that may provide false positive staining, the tumor-promoting effects of the EPO/EPOR axis have remained an outstanding issue." (PMID 35694408, 2022). "EPO plays a role in promoting proliferation in hematopoietic progenitor cells and may also promote the growth of tumor cells, thus promoting tumor progression and metastasis, leading to poor prognosis of patients." (PMID 35359375, 2022). "However, later scientific evidence shows that EPO treatment in cancer patients mediates a variety of serious adverse effects, including survival decrease, acceleration of tumour progression and an increase in the incidence of thromboembolic events." (PMID 35626116, 2022). "EPO enhances tumor growth and progression via activation of EphB4 signaling." (PMID 34953452, 2022). "In tumor metastasis, EPO also plays an important role and may regulate the JAK/STAT and ERK1/2 pathways." (PMID 33816287, 2021). "Moreover, the hypoxic microenvironment of cancer tissues stimulates the local EPO production, supporting viability and independent tumor growth." (PMID 34299300, 2021). "However, the EPO production mechanisms of the hiPSC-EPO cells used in this study are expected to be more physiologically relevant than those of tumor cell lines." (PMID 33594180, 2021). "Elevated Erythropoietin levels have also been described in other patients with UESL which could be attributed to the mesenchymal origin of this tumor." (PMID 34162402, 2021). "Furthermore, the expression levels of EPO and EPO-R in tumor tissues have been proposed as possible prognostic and predictive molecular indicators in tumor patients." (PMID 32922549, 2020). "On the other hand, it is speculated that tumor-related inflammation may result in the release of various inflammatory factors, which may affect erythropoietin synthesis and lead to the decrease in HGB." (PMID 32192483, 2020). "it has been reported that EPO could switch on tumor angiogenesis just by activating JAK2/STAT5 and PI3K/Akt signal pathways." (PMID 30915348, 2019). "Serving as the malignant solid tumor of female reproductive tract, CSCC could widely and strongly express EPO/EPO-R to induce tumor angiogenesis, thus promoting cancer progression." (PMID 30915348, 2019). "All EPO-TAMNLC dosages markedly reduced tumor sizes after two weeks of treatment." (PMID 31291309, 2019). "However, when we stained for ALDH1A3, a known marker for breast CICs, we found serum erythropoietin levels negatively correlated with the number of putative breast CICs in the tumor sections." (PMID 30700319, 2019). "Considering VM is another pattern of tumor microcirculation, there are, however, few report concerning whether EPO/EPO-R promotes tumor VM formation too." (PMID 30915348, 2019). "The role of EPO signaling on tumor growth remains unclear nowadays, which is partly due to undefined EPO-R expression pattern in tumor cells." (PMID 31752873, 2019). "HIF-1 activates many target genes, and HIF-1-regulated gene products (i.e., vascular endothelial growth factor, epidermal growth factor, erythropoietin, glucose transporters, and glycolytic enzymes) facilitate tumor survival, proliferation, invasion, and metastasis." (PMID 30719182, 2019). "EPOR protein expression and EPO level were notably increased in the patient’s tumor tissue as well." (PMID 29534684, 2018).
tumor (continued). "Ephrin, which is also known as erythropoietin-producing human hepatocellular receptor, manages multiple processes that are essential for tissue homeostasis or development, is widely expressed in cancer tissues, and plays a role in the tumor microenvironment." (PMID 30020984, 2018). "Furthermore, the phosphorylation levels of EPOR and STAT5 in these 14 tumor specimens were significantly increased compared to that in the remaining 21 tumor specimens from the patients whose serum EPO was at low level or remained unchanged after surgery." (PMID 29137269, 2017). "In this article we review the effect of EPO on ECs in ischemic heart neovascularization and in retinal revascularization of injured vasculature, as well as its effect on neural progenitor cells, on tumor angiogenesis, and in other pathological conditions." (PMID 28703764, 2017). "In addition, mice with H1819-shEPOR xenograft tumors had significantly reduced human EPO in serum suggesting the delay of tumor growth led to the decrease of endogenous EPO." (PMID 29137269, 2017). "Although EPOR expression on tumor cells is typically several orders of magnitude lower than on erythroid progenitor cells, EPO can still activate cell signaling cascades in tumor cells, such as in differentiated neuroblastoma SH-SY5Y cells, which have fewer than 50 EPOR dimers on their cell surface." (PMID 28418910, 2017). "Three weeks after tumor resection, serum EPO of these 16 patients were measured again." (PMID 29137269, 2017). "They showed that EPO can stimulate both lymph node lymphangiogenesis and nodal metastasis by increased migration, capillary-like tube formation, and dose- and time-dependent proliferation of human lymphatic ECs in tumor-bearing animals." (PMID 28703764, 2017). "Our in vitro studies suggest that EPO-mediated activation of eIF4E may play an important role in tumor cell proliferation." (PMID 28415825, 2017). "Furthermore, the supernatants of the primary tumor cell cultures from these 14 patients had higher EPO concentrations than those from the other 21 patients." (PMID 29137269, 2017). "In summary, we have illustrated EPO could be directly secreted from the tumors of a subgroup of NSCLC patients, and the tumor derived EPO was capable of promoting the dual EPO and EPOR-positive NSCLC progression." (PMID 29137269, 2017). "In addition, correlated analysis indicated that the expression of KIAA0101 and EPO expression was positively in clinical tumor samples." (PMID 26575329, 2016). "Importantly, the presence of focal stromal cell membranous pJAK2 in localized clusters of tumor cells with increased levels of EPO-R activation suggests paracrine effects of EPO in regions of local activation." (PMID 27748427, 2016). "The systematic identification of pathway differences and sensitivities of EPOR signaling in CFU-E and H838 cells revealed potential targets for intervention to selectively inhibit EPO-induced signaling in the tumor cells but leave the responses in erythroid progenitor cells unaffected." (PMID 27494133, 2016). "Another hypoxia factor HIF-2α was also associated with tumor induced EMH, it could induce erythropoietin (EPO) production and mediate tumor-related splenic erythropoiesis." (PMID 27708244, 2016). "Simultaneous quantifications of multiparameter obtained from the same microscopic areas indicated that 50 IU/mL EPO dramatically increases tumor cell counts (BrdU) and DNA content (DAPI, 2N verse 4N), which illustrates that r-Hu EPO promotes 786-O and Caki-2 cells proliferative activity." (PMID 26575329, 2016). "Statistical analysis showed significant increase of tumor MVD in erythropoietin-treated DLD-1 xenografts compared with control DLD-1 xenografts (p < 0.05) and compared with Ht-29 xenografts (p < 0.001), as well as in control DLD-1 xenografts compared with Ht-29 xenografts (p < 0.005)." (PMID 27543111, 2016).
tumor (continued). "However, recent evidence from clinical studies suggested that EPO accelerated tumor progression and jeopardized the 5-year survival." (PMID 26575329, 2016). "Another group of factors that may direct migration of RMS cells are cytokines, and our recent research demonstrated the involvement of erythropoietin in enhancing the pro-metastatic potential of this tumor." (PMID 27510263, 2016). "Our results suggest that the increased tumour growth during erythropoietin treatment might be due to inhibition of apoptosis, an effect that becomes significant during tissue damage such as surgery." (PMID 25182342, 2014). "Similarly, EPO has also been reported to have other effects in addition to its role in erythropoiesis, including the promotion of tumor cell growth and survival." (PMID 25120692, 2014). "Superselective embolization of the tumor significantly decreased the sEPO level, suggesting that the hypervascular lesion in the left kidney may be the origin of abnormal EPO production." (PMID 25295086, 2014). "We add a third potential mechanism and this is direct effect of EPO on cancer stem and/or TICs, which could explain enhanced tumor progression and poor survival of some cancer patients treated with EPO." (PMID 25426117, 2014). "As EPOR is present in various cancer cells, the use of rHuEPO in cancer patients may be problematic due to potential activation of EPO-EPOR signaling pathways resulting in tumor protection (anti-apoptotic action) or proliferation (mitogenic action)." (PMID 25426117, 2014). "With the current experimental model, we not only analyzed the progressive changes in EPO gene expression and protein production during chronic liver damage and tumor development, but also attempted to identify the cellular sources and the probable targets of the hematopoietic hormone." (PMID 23052842, 2013). "The re-evaluation of large cohorts with respect to EPO and hypoxic state of the tumor could shed light on this phenomenon and help direct future clinical trials." (PMID 24004818, 2013). "Interestingly through, the patient continued on EPO (4000 u/WK) and remained tumour-free for more than 9 months." (PMID 23305401, 2013). "Interestingly, already after 4 weeks of treatment, the expression started to increase and became statistically significant at week 8, therefore indicating an EPO overproduction preceding the appearance of tumor." (PMID 23052842, 2013). "To determine whether EPO can regulate tumor growth and proliferation in vivo, we injected subcutaneously Caki-1, 786-O and 769-P cells in athymic nude mice, however, 769-P cells did not form subcutaneous tumors in this model." (PMID 24004818, 2013). "Moreover, immunoreactivity for PCNA in EPO treated xenografts showed that tumor cells in peri-vessel areas displayed higher proliferation, which was indicated as increased PCNA staining." (PMID 22086127, 2012). "Several studies have also reported that recombinant human erythropoietin might have a proliferative or survival-promoting effect on tumours." (PMID 20051958, 2010). "Whether systemic treatment with agents targeting erythropoietin, such as purified R103A-EPO antagonist protein, can produce regression of high tumor burdens and/or prevent metastasis remains to be determined." (PMID 17579721, 2007). "We investigated whether protein inhibitors targeting EPO function could suppress tumor-cell induced neovascularization and delay growth." (PMID 17579721, 2007). "The suppression of tumor angiogenesis and progression by erythropoietin blockade suggests that erythropoietin may constitute a potential target for the therapeutic modulation of angiogenesis in cancer." (PMID 17579721, 2007). "Erythropoietin or its antagonist proteins were co-injected with tumor cells into window chambers." (PMID 17579721, 2007).